PPARA (peroxisome proliferator activated receptor alpha)
Diseases named in the same sentence as PPARA in open-access papers (continued):
Sharing a sentence is not in itself a finding about the gene and the disease.
liver fibrosis (106 papers, 2012 to 2025). "Moreover, hepatic fibrosis caused by arsenic trioxide induces the activation of HSCs through PPARα activation and autophagy, where taurine supplementation alleviates this response." (PMID 39768147, 2024). "Furthermore, TSP-1 deficiency mediated modulation of PPARα pathway in CDAHFD induced hepatic fibrosis were observed in both physiological and transcriptomic data." (PMID 31891606, 2019). "Although the PPARα‐catalase pathway has been reported in the treatment of alcoholic liver disease, hepatic fibrosis, and skin aging, this study is the first to elucidate its role in mitigating FC‐induced oxidative stress in NAFLD through DhT treatment." (PMID 39558866, 2025). "The dual PPARα/γ activation by saroglitazar is likely responsible for the attenuation of hepatic fibrosis by promoting fatty acid oxidation, reducing hepatocellular inflammation, and decreasing hepatic lipid deposition." (PMID 41583325, 2025). "Sirius Red staining and CD68 immunofluorescence staining consistently showed that PPARα inhibition reversed the improvement exerted by Fat-1 on liver fibrosis and inflammation." (PMID 40052160, 2025). "Inhibition of PPARα can lead to lipid metabolism disorder and promote the progression of hepatic fibrosis." (PMID 38813108, 2024). "In this regard, it has been demonstrated that oleoylethanolamide, an endocannabinoid-like molecule, attenuates the progress of liver fibrosis by blocking HSC activation through PPARα activation." (PMID 39768147, 2024). "Activation of PPARα can accelerate the breakdown of aliphatic acids and inhibit activation of hepatic stellate cells, reducing the severity of hepatic fibrosis." (PMID 38813108, 2024). "In a phase 2 clinical trial, the PPARα/δ dual agonist elafibranor improves lipid metabolism and reduces inflammation, which delays liver fibrosis in non-alcoholic steatohepatitis (NASH) patients." (PMID 37576819, 2023). "Fenofibrate attenuates liver fibrosis in mice by activating PPARα and enhancing FAO in macrophages, which drives their polarization to M2 macrophages." (PMID 37576819, 2023). "In nonalcoholic steatohepatitis (NASH) diseases, which include liver fibrosis and liver cancer, the composition of the cell membrane and the PPARα and the methylation pattern of DNA is also important." (PMID 35215560, 2022). "In particular, LV extract ameliorated liver fibrosis effectually in comparison with a dual PPARα/δ agonist (GFT 505)." (PMID 33494735, 2021). "By mapping the candidate targets to the 66 known genes associated with hepatic fibrosis obtained from OMIM and DrugBank, 10 co-targets were found, including HSP90AA1, PPARG, MAPT, HSP90AB1, STAT1, and PPARA." (PMID 33510287, 2021). "PPARα and PPARδ play an important role in suppressing liver fibrosis by inhibiting liver steatosis and inflammation." (PMID 34746195, 2021). "Among them, the anti-inflammatory N-acyl ethanolamide (NAE)-peroxisome proliferators activated receptor alpha (PPARα) system has gained much interest after the identification of its protective role in steatohepatitis and liver fibrosis." (PMID 29056914, 2017). "We evaluated the role of PPARα in the development of liver fibrosis by assessing the hepatic expression of α-smooth muscle actin (α-SMA), a well-known marker of activated HSCs." (PMID 23388073, 2013). "The aim of this study was to elucidate the effect and the molecular basis of PPARα in ethanol induced liver fibrosis in mice." (PMID 23388073, 2013). "In the present study, the underlying molecular mechanisms of ethanol induced hepatic fibrosis and the effect of PPARα in the pathogenesis of alcohol-induced liver fibrosis were elucidated." (PMID 23388073, 2013). "Nine muscle pathways were identified, including inflammatory (hepatic fibrosis and IL-6), lipid metabolic (PPARα, PPARγ and sphingolipids) and carbohydrate metabolic (pyruvate and propanoate) pathways." (PMID 23251491, 2012).
liver fibrosis (continued). "Queries of ROBOKOP returned several paths relating clofibrate, PPARA, and hepatic fibrosis." (PMID 40330554, 2025). "Apigenin alleviated liver fibrosis by inhibiting p38/PPARα pathways in hepatic stellate cells." (PMID 39334795, 2024). "The study demonstrated that PPARα activation attenuated liver fibrosis by reducing the expression of pro-inflammatory cytokines and chemokines, including CXCR1 and CXCR2, thus highlighting the potential link between PPARα and CXCR1/2 in liver inflammation and fibrosis." (PMID 39627194, 2024). "Lanifibranor, the PPARα/δ/γ pan agonist developed by Inventiva (Daix, France), was first described for its prevention of experimental skin and lung fibrosis, and was then applied to liver fibrosis." (PMID 37627519, 2023). "Importantly, like FBXW7, PPARA expression declines as NASH progresses and is significantly reduced in liver fibrosis, cirrhosis, and HCC, with low PPARA expression associated with a poor survival rate among HCC patients." (PMID 37914694, 2023). "Similarly, PPARα activation also inhibits hepatic fibrosis by suppressing Smad2/3 phosphorylation via inhibiting the expression of α-SMA and collagen." (PMID 34938805, 2021). "Moreover, IPA analysis retrieved a list of the top upstream regulators, where peroxisome proliferator-activated receptor alpha (PPARα) is the most significant upstream regulator altered after CCl4-induced liver fibrosis, followed by c-Myc." (PMID 33261190, 2020). "Furthermore, oleoylethanolamide, an endocannabinoid-like endogenous molecule that binds PPARα with high affinity, ameliorated thioacetamide-induced hepatic fibrosis in a PPARα-dependent manner." (PMID 32192216, 2020). "In addition, PPARα is required for the anti-inflammatory actions of PEA, and presence of PPARα mRNA in HSCs and suppressive effect of PPARα agonist Wy-14,643 on liver fibrosis have been reported." (PMID 30057547, 2018). "In hepatic stellate cells (HSCs), which are the main nonparenchymal liver cells contributing to the abnormal extracellular matrix deposition in liver fibrosis, miR-33 and miR-27a/-27b were also found upregulated and to target PPARα and the PPARα cofactor RXR, respectively." (PMID 28167956, 2017). "Several studies have also reported that PPARα activation attenuates liver fibrosis." (PMID 29056914, 2017). "Moreover, OEA was described to suppress the pro-fibrotic cytokine TGF-β1 signaling in mouse models of hepatic fibrosis, an improvement that was lost in PPARα knockout mice." (PMID 29056914, 2017). "Further research is needed to determine whether PPARα can also affect the other mediators of hepatic fibrosis." (PMID 28159867, 2017). "With the progression of liver fibrosis, hepatic PPARα expression was reduced, suggesting that abnormal expression and/or dysfunction of PPARα might be involved in the development of ethanol plus CCl4 induced liver injury." (PMID 23388073, 2013). "We queried ROBOKOP to first establish that it could demonstrate a relationship between clofibrate and PPARA as a validation test and second to identify intermediary genes and biological processes or activities that might relate the activation of PPARA by clofibrate to hepatic fibrosis." (PMID 40330554, 2025). "This study aimed to apply ROBOKOP to suggest biological mechanisms that might explain the hypothesized relationship between exposure to the herbicide and lipid-lowering drug clofibrate, an activator of peroxisome proliferator-activated receptor-α (PPARA), and hepatic fibrosis." (PMID 40330554, 2025). "It has been hypothesized that the weak effect of PPARα agonists in human could be related to the lower expression of PPARα in human liver compared to mouse or to an inverse correlation between progressive stages of liver fibrosis and hepatic PPARα." (PMID 31703268, 2019). "In an experimental model of mouse liver fibrosis, OEA mitigates liver fibrosis by targeting hepatic stellate cells via a PPARα-dependent pathway." (PMID 40474970, 2025).
liver fibrosis (continued). "Consistently, mixed PPARα/γ agonists regulate inflammatory cytokines by inhibiting TGF-β1, alleviating liver fibrosis." (PMID 40642530, 2025). "This study provides novel insights into the effects of a PPARα agonist on intestinal LCFA absorption and hepatic fibrosis in MASH model rats." (PMID 40389836, 2025). "Recently, the dual AdipoR1/AdipoR2-based agonist JT003 has been demonstrated to enhance fatty acid oxidation and glucose uptake and mitigate liver fibrosis and insulin resistance in mice via signaling pathways, including AMPK, PPARα, and AKT." (PMID 39737222, 2024). "Hepatic PPARA expression is positively correlated with FBXW7 in patients with NAFL, NASH, liver fibrosis, and HCC, implying their close association and pivotal contribution to liver health." (PMID 37914694, 2023). "Nowadays, PPARA is regarded as a vital target for non-alcoholic steatohepatitis (NASH) and liver fibrosis." (PMID 35264957, 2022). "Previous reports have shown that PPARα expression is reduced in the liver of NASH patients, and PPARα activation inhibits liver fibrosis in mice." (PMID 33424957, 2020). "PPARα activation can confer liver protection in disease models of non-alcoholic steatohepatitis (NASH), alcohol liver disease (ALD) and liver fibrosis." (PMID 29056914, 2017). "Interestingly, PPARα has been reported as a potential strategy to counteract fibrosis, contributing to the ECM deposition during EP and PP and liver fibrosis during late E. stiedae infection." (PMID 40303088, 2024). "Owing to the protective effects of FGF21 on cholestasis-induced liver fibrosis, we further analyzed the beneficial effects of NaB, a well-known gut-microbiota-derived SCFA, to induce FGF21 expression in the liver through activation of PPARα." (PMID 39040469, 2024). "In 2017, IVA337, another new PPAR (including PPARA) agonist, revealed its ability to suppress the proliferation and activation of human hepatic stellate cells (HSCs), and alleviate mouse liver fibrosis induced by CCL4." (PMID 35264957, 2022). "The EtOH-fed+DNLA group displayed more activation of PPARα and PXR/RXRα than the EtOH-fed group, suppressed the upregulation of hepatic fibrosis signaling and death receptor signaling, and prevented the downregulation of the antioxidant action of vitamin C in the EtOH-fed group." (PMID 36359319, 2022). "Activation of the TGFβ pathway is closely associated with low expression of PPARα and NR1H4, indicating that enhancing PPARα and NR1H4 levels may delay the progression of liver fibrosis." (PMID 36090996, 2022). "Apigenin could alleviate liver fibrosis by inhibiting hepatic stellate cell activation and autophagy via TGF-β1/Smad3 and p38/PPARα pathways." (PMID 33574836, 2021). "PPARγ agonist ameliorates LSECs activation and inflammation; while PPARβ/δ and PPARα agonists induce ICAM-1 expression in non-stimulated ECs playing an important role in liver fibrosis." (PMID 34361064, 2021). "Our current results confirmed that apigenin could ameliorate liver fibrosis by inhibiting autophagy via the TGF-β1/Smad3 and p38/PPARα pathways." (PMID 33574836, 2021). "In our results, we found that liver fibrosis induced by CCl4 and BDL surgery could lead to phosphorylation of p38, which further inhibited PPARα." (PMID 33574836, 2021). "Another important miRNA is miR-155, a major regulator of increased Kupffer cell activation and TNF-α production, and is also involved in ethanol-induced liver fibrosis and steatohepatitis by mediating the peroxisome proliferator-activated receptor response element (PPRE) and PPARα pathway." (PMID 34068269, 2021). "We hypothesized that apigenin could alleviate liver fibrosis by inhibiting hepatic stellate cell activation and autophagy via TGF-β1/Smad3 and p38 MAPK/PPARα pathways." (PMID 33574836, 2021). "Our results indicate that AdipoRs dual agonist JT003 with a longer half-life could ameliorate NASH and related liver fibrosis via AMPK, PPARα and PI3K-Akt signal pathways." (PMID 33199780, 2020).
liver fibrosis (continued). "We found that AESN elevated PPARα and PGC-1α mRNA levels in HFD/ethanol-induced rats, and inhibited the decrease in ACC, FAS, and ChREBP mRNA levels, thereby improving hyerlipidemia and suppress HSCs activation and hepatic fibrosis." (PMID 26927042, 2016). "We demonstrated that PPARα agonist significantly repressed hepatic expression of visfatin, and consequently reduced PI3K, MMP-2 and MMP-9 expression, thus suppressing the progression of ethanol mediated liver fibrosis." (PMID 23388073, 2013). "Therefore, we can draw the conclusion that apigenin could relieve hepatic fibrosis induced by CCl4 and BDL via downregulating the TGF-β1/Smad3 and p38/PPARα pathways." (PMID 33574836, 2021).
heart failure (94 papers, 2008 to 2025). Inability of the heart to pump blood at an adequate rate to meet tissue metabolic requirements. "The use of PPARα agonists correlates with a risk factor in heart failure due to its persistent dependence on plasma lipid reduction and recovery of dysfunctional cardiac activities." (PMID 37189744, 2023). "This suggests that the upregulation of glucose metabolism from intrinsic responses to PPARα deficiency or from glucose transporter overexpression has different effects on heart failure." (PMID 37233656, 2023). "PPARα plays a central role in FA metabolism in the heart, and cardiac-specific PPARα-deficient mice exhibit impaired FA metabolism and heart failure." (PMID 35055179, 2022). "Although dual PPARα/γ agonist glitazars can lower plasma glucose and triglycerides, they have been associated with heart failure." (PMID 34641558, 2021). "For example, decreased fatty acid oxidation due to reduced PPARα expression in the heart results in cardiac energy deficiency, which is associated with heart failure." (PMID 30469494, 2018). "Supplementation with ω-3 PUFA, which are ligands for PPARα, could activate expression of genes encoding mitochondrial enzymes, thereby reducing the impairment of myocardial energy metabolism observed with heart failure." (PMID 20819225, 2010). "Reduced PPARα expression and excessive mitochondrial fatty acid oxidation contribute to alterations such as heart failure, ischemic heart disease, and diabetic cardiomyopathy." (PMID 41008965, 2025). "Specifically, in conditions such as heart failure and diabetic cardiomyopathy, PPARα gene expression is downregulated, and the concentrations of PPARα and PGC-1α are reduced." (PMID 39125938, 2024). "PPARα expression is relatively decreased in heart failure patients with hypertensive heart disease compared to patients with normal cardiac function." (PMID 37233656, 2023). "This different response derives from a sex-dependent regulation of the PPARα signaling pathway in heart failure." (PMID 37233656, 2023). "In contrast, PPARα activation by inducible transgenic mice maintains myocardial function with enhanced FAO in the early stages of heart failure." (PMID 37233656, 2023). "Myocardial fatty acid oxidation decreased and glucose utilization increased in patients with severe heart failure, and PPARα expression was significantly reduced in left ventricular tissue biopsied from patients with severe heart failure." (PMID 35153792, 2022). "Subsequently, when PPARα is upregulated under stress conditions (i.e., heart failure or an HFD), PPARα is able to bind to other proteins, including RXR and SIRT1." (PMID 36551797, 2022). "After pre-protection in zebrafish by quinic acid, low mRNA expression of PPARA was observed, suggesting that PPARA activation during heart failure improved myocardial function and energetics." (PMID 36313322, 2022). "Heart failure activates PPARA to regulate fatty acid metabolism and provide energy for cardiomyocytes." (PMID 36313322, 2022). "One experimental study elucidated the effects of chronic PPARα activation using fenofibrate in heart failure after induced myocardial infarction in rats." (PMID 33322384, 2020). "Studies have found that reduced PPARA expression during heart failure leads to reduced fatty acid oxidation and myocardial energy deficiency." (PMID 31772600, 2019). "PPAR agonist treatment is mostly beneficial in animal models of heart failure, but the beneficial or aggravating role of PPARα activation in ischemia/reperfusion remains controversial." (PMID 26713088, 2015). "PPARα is reduced in heart failure, shifting cardiac energy utilization from fatty acid to glucose." (PMID 39242479, 2024).